FCGBP (Fc gamma binding protein)
Diseases named in the same sentence as FCGBP in open-access papers (continued):
Sharing a sentence is not in itself a finding about the gene and the disease.
lung carcinoma (5 papers, 2022 to 2025). "FCGBP alternative splicing and FCGBP mutations may implicate the pathogenesis of lung cancer and hepato-cholangiocarcinoma, respectively." (PMID 35626334, 2022). "The second one is that the alternative splicing of FCGBP mRNA is detected in lung cancer, hepato-cholangiocarcinoma, CRC, and brain arteriovenous malformations." (PMID 35936008, 2022). "We highlight the increased expression of immune-response-related genes FCGBP, BPIFB, F5, CST1, and CFB, and their correlation to epithelial-to-mesenchymal transition (EMT) under SMG, rendering them potential biomarkers of lung cancer progression." (PMID 36613598, 2022). "FCGBP, BPIFB1, F5, CFB, and CST1 and their correlation to EMT key markers displayed a potentially less metastatic phenotype of lung cancer under SMG." (PMID 36613598, 2022). "In addition, the alternative splicing of FCGBP mRNA has been detected in patients with smoking-induced lung cancer, raising the possibility that this phenomenon may play a role in the pathogenesis of lung cancer." (PMID 35936008, 2022). "Interestingly, we also showed that these genes correlate to the overall survival of lung cancer patients, where some showed significant correlation to poor prognosis and others showed no potential correlation, except for FCGBP, which was significantly associated with better prognosis." (PMID 36613598, 2022). "Overall, these data imply that the differentially expressed FCGBP, F5, CFB, and BPIFB1 in lung cancer may play an important role in lung cancer progression." (PMID 36613598, 2022).
ulcerative colitis (5 papers, 2021 to 2024). An inflammatory bowel disease involving the mucosal surface of the large intestine and rectum. "The initial connections between FCGBP and CRC stem from its involvement in ulcerative colitis, a chronic inflammatory condition predisposing the individuals to CRC." (PMID 38709264, 2024). "The level of FCGBP antigen in the serum of patients with ulcerative colitis and Crohn’s disease reflects the pathophysiologic state and can be used as a diagnostic marker for these autoimmune diseases." (PMID 35936008, 2022). "In Crohn’s disease and ulcerative colitis, the heightened expression of FCGBP may signify pathophysiologic changes in CRC development." (PMID 38709264, 2024). "To assess if the phenomenon we observed in human LS174T goblet-like cells was true of more complex and relevant diseases, the expression of MUC2/FCGBP was determined from human biopsy samples taken from healthy controls and patients with active ulcerative colitis (UC) and UC in remission (UC-R)." (PMID 37359538, 2023). "First, the elevated expression of FCGBP may reflect pathophysiologic changes in Crohn’s disease and ulcerative colitis, but the mRNA and protein expression of FCGBP are decreased in colorectal adenomas and cancers." (PMID 35936008, 2022). "Altered FCGBP expression levels may be important in the pathologic processes of Crohn’s disease and ulcerative colitis." (PMID 35936008, 2022). "Interestingly, FCGBP is overexpressed in the intestinal crypts of ulcerative colitis patients." (PMID 34332619, 2021). "A significantly increased expression of FCGBP, CLCA1, and TFF3 was detected in the serum of patients suffering from ulcerative colitis and Crohn’s disease." (PMID 35936008, 2022).
adenoma (4 papers, 2014 to 2022). A neoplasm arising from the epithelium. "Upregulated in adenoma samples was a cluster of the proteins FCGBP, SGSH, MUC2, and PRSS8 when compared to adenomas, of which the latter two are known to play an important role in maintaining a healthy colonic epithelium." (PMID 36369736, 2022). "FcGBP, was found to be downregulated in our study and in normal-adenoma-carcinoma sequence according to Lee and colleagues." (PMID 33648461, 2021). "The ratio of positive FcGBP expression was significantly down-regulated in gallbladder adenocarcinoma (48.1 %) than in peritumoral tissues (76.1 %), adenoma (80.0 %), polyps (86.7 %) and chromic cholecystitis (85.7 %) (P < 0.05)." (PMID 24310606, 2014). "Furthermore, FCGBP has previously displayed down-regulation especially in the normal-adenoma-carcinoma sequence." (PMID 36369736, 2022).
colorectal adenoma (4 papers, 2021 to 2023). An adenoma that arises from the colon or rectum. "Reduced expression of FCGBP was frequently observed in colorectal adenoma and CRC." (PMID 37182141, 2023). "In summary, this study identified a set of differentially expressed genes in CRC, including FcGBP, CLCA1, ADH1C, COL1A1, ZG16, which could be strong candidates to be used as biomarkers of colorectal adenoma-adenocarcinoma progression." (PMID 33648461, 2021).
glioblastoma (4 papers, 2021 to 2023). The most malignant astrocytic tumor (WHO grade IV). "In addition, it has been described an inflammatory biomarker signature, including FCGBP, in small extracellular vesicles isolated from blood samples of glioblastoma patients." (PMID 36371440, 2022). "However, FCGBP showed a significantly high expression in glioblastoma (GBM) compared with normal tissues." (PMID 35047393, 2021).
asthma (3 papers, 2021 to 2024). "We also identified three highly upregulated proteins (with fold changes of over 25), FCGBP, ALOX15, and SERPINB2, which play critical roles in human allergy, immune responses, and asthma." (PMID 38732251, 2024).
gallbladder adenocarcinoma (3 papers, 2014 to 2024). A carcinoma that arises from glandular epithelial cells of the gall bladder. "On the basis of the dramatic fold changes, NT5E and FCGBP were selected and then reexamined by the use of RT-PCR and Western blot, which employed specimens of patients diagnosed as having gallbladder adenocarcinoma and chronic cholecystitis." (PMID 24310606, 2014). "NT5E expression was upregulated and FcGBP expression was downregulated in gallbladder adenocarcinoma compared to chronic cholecystitis in vivo, which was consistent with the DNA microarray data." (PMID 24310606, 2014). "The monovariable Kaplan–Meier survival analysis suggested that NT5E and FcGBP expression were significantly related to the average survival time of patients with gallbladder adenocarcinoma." (PMID 24310606, 2014). "Then, an in-vivo study of gallbladder adenocarcinoma and chronic cholecystitis was performed to verify the results obtained in the microarray study and further investigate the role of NT5E and FcGBP in invasion and metastasis of gallbladder adenocarcinoma." (PMID 24310606, 2014). "The elevated expression of NT5E and decreased expression of FcGBP in gallbladder adenocarcinoma suggested that they are important markers for progression, clinical biological behavior and prognosis." (PMID 24310606, 2014). "Immunochemistry and clinicopathological results showed that the expression of NT5E and FcGBP in gallbladder adenocarcinoma is an independent marker for evaluation of the disease progression, clinical biological behaviors and prognosis." (PMID 24310606, 2014). "In addition, FCGBP protein has an independent prognostic profile in gallbladder adenocarcinoma and metastatic colorectal cancer." (PMID 38396056, 2024). "The in-vivo study of gallbladder adenocarcinoma and chronic cholecystitis was performed to verify the expression levels of NT5E and FcGBP in invasion and metastasis of gallbladder adenocarcinoma." (PMID 24310606, 2014).
thyroid cancer (3 papers, 2017 to 2022). "Another supporting finding is that FCGBP in thyroid cancer can functionally synergize with TFF3 through genetic co-expression, and thus contributing to poor survival in thyroid cancer patients with low TFF3 level." (PMID 35626334, 2022).
amyotrophic lateral sclerosis (2 papers, 2022 to 2024). Amyotrophic lateral sclerosis (ALS) is a neurodegenerative disease characterized by progressive muscular paralysis reflecting degeneration of motor neurons in the primary motor cortex, corticospinal tracts, brainstem and spinal cord. "FCGBP has therefore been related to amyotrophic lateral sclerosis, a fatal disorder caused by the progressive degeneration of motoneurons in the brain and spinal cord, by facilitating autoimmune and neuroinflammatory responses." (PMID 36371440, 2022).
brain arteriovenous malformation (2 papers, 2022). "Genetic variations of FCGBP are also found in cerebral arteriovenous malformations." (PMID 35936008, 2022).
follicular thyroid carcinomas (2 papers, 2013 to 2021). "The Fc fragment of the IgG binding protein (FcγBP, FCGBP) is expressed in the normal thyroid and is down-regulated in papillary and follicular thyroid carcinomas." (PMID 34442426, 2021).
hepatocellular carcinoma (2 papers, 2023 to 2024). A malignant tumor that arises from hepatocytes. "However, the specific role of FCGBP in hepatocellular carcinoma (HCC) remains undefined." (PMID 36803544, 2023).
intra-amniotic infection (2 papers, 2021). "The protein concentrations of IgGFc-binding protein (FcγBP), which is a core mucus protein with anti-inflammatory properties, in the cervical fluid were also elevated in the presence of intra-amniotic infection in patients with PPROM (presence: 345 ng/mL vs. absence: 60 ng/mL)." (PMID 35118439, 2021).
Obesity (2 papers, 2022 to 2024). Accumulation of substantial excess body fat. "A recent meta-nalysis reporting AT epigenetic profile in obesity showed that FCGBP gene is hypomethylated in metabolically unhealthy individuals with overweight or obesity." (PMID 38703299, 2024). "FCGBP protein abundance was found increased in endometrial tissue of women with obesity compared to normoweight matching controls but decreased in EVs of a similar population of women with obesity." (PMID 38703299, 2024).
viral infections (2 papers, 2020 to 2024). "Among the other five genes, FCGBP, which encodes Fc fragment of IgG binding protein, has been reported with virus infection and viral vector design." (PMID 33178176, 2020). "FCGBP is a highly up-regulated defense gene after bacterial or viral infections and could influence the adherence of microorganisms as well as their clearing." (PMID 38396964, 2024).
astrocytomas (1 paper, 2022). "Interestingly both FCGBP and SERPINA1 have been proposed as GB-associated genes due to their upregulation in primary and secondary GBs compared to lower-grade astrocytomas." (PMID 35052804, 2022).
colitis (1 paper, 2023). Inflammation of the colon. "The disappearance of FCGBP and MUC2 during the restitutive phase of DSS colitis suggests that both molecules are tightly regulated and may have a long-lasting impact during tissue healing and in epithelial barrier function." (PMID 37359538, 2023). "In wound healing assays and an animal model of colitis, cytoplasmic FCGBP not bound to MUC2 played an endogenous role in wound healing to maintain epithelial barrier function." (PMID 37359538, 2023).
dementia (1 paper, 2025). Loss of intellectual abilities interfering with an individual's social and occupational functions. "Other genes previously associated with AD or dementia were differentially expressed in both brain regions: CHI3L2, FCGBP, GLI1, STAB1, APOC1, MYO7A, and long non‐coding RNA JHDM1D‐AS1." (PMID 39876821, 2025).
ependymoma (1 paper, 2025). A WHO grade II, slow growing tumor of children and young adults, usually located intraventricularly. "FCGBP mutations occurred at a frequency of 28% across all three ependymoma subtypes and the potential functional significance demanding further mechanistic study." (PMID 41160379, 2025).
gastric cancer (1 paper, 2022). A primary or metastatic malignant neoplasm involving the stomach. "We found that the methylated region of FCGBP gene is located in the fifth exon region inside the gene, which may be involved in the regulation of gene expression and affect its function on LNM in gastric cancer." (PMID 35115040, 2022).
gastritis (1 paper, 2025). Inflammation of the stomach. "Collectively, these findings suggest that the four biomarkers, namely, CHI3L1, FCGBP, VSIG2, and TFF2, hold the potential for diagnosing GC, particularly in cases of gastritis and early‐stage GC." (PMID 40084401, 2025).
glaucoma (1 paper, 2023). Increased pressure in the eyeball due to obstruction of the outflow of aqueous humor. "Second, among the 13 upregulated markers, many were already reported in the AH of patients with glaucoma (e.g., TIMP1, FCGBP)." (PMID 37895034, 2023).
HIV-1 infection (1 paper, 2024). The type species of lentivirus and the etiologic agent of acquired immunodeficiency syndrome (AIDS). "For example, copy number variations in the FCGBP gene have been hypothesized as being the cause for resistance to HIV-1 infection observed in a group of women in Kenya." (PMID 38396964, 2024).
human papillomavirus infection (1 paper, 2022). "A high FCGBP level is significantly associated with better overall- and disease-specific-survivals, regardless of human papillomavirus infection." (PMID 35626334, 2022).
inflammatory bowel disease (1 paper, 2020). A spectrum of small and large bowel inflammatory diseases of unknown etiology. "FCGBP function as a mucin-like glycoprotein cooperated with MUC2, both of which were crucially essential part of mucus layers of the colon barrier, and might play a role in cell protection and inflammatory bowel disease." (PMID 31956350, 2020).
intestinal tumor (1 paper, 2021). "The Fc Fragment of IgG Binding Protein (FCGBP) has been proven to participate in intestinal tumor immunity." (PMID 35047393, 2021).
liver cancer (1 paper, 2023). An epithelial or non-epithelial malignant neoplasm that arises from the liver. "Additionally, aberrant FCGBP expression was found in most human cancers, including liver cancer." (PMID 36803544, 2023).
mucinous adenocarcinoma (1 paper, 2023). An invasive adenocarcinoma composed of malignant glandular cells which contain intracytoplasmic mucin. "Our results indicate that mucinous adenocarcinoma cancer cells have goblet cell-like properties, and express high levels of goblet cell markers (REG4, SPINK4, FCGBP and MUC2) compared to classical adenocarcinoma cancer cells." (PMID 36690709, 2023).
non-small cell lung carcinoma (1 paper, 2025). A group of at least three distinct histological types of lung cancer, including non-small cell squamous cell carcinoma, adenocarcinoma, and large cell carcinoma. "In non-small cell lung cancer, FCGBP exhibits the highest mutation frequency among smoking-related genes, with its downregulation strongly correlating with enhanced tumor proliferation, migration, and immunosuppressive microenvironments in smokers." (PMID 41160379, 2025).
ovarian serous adenocarcinoma (1 paper, 2024). An adenocarcinoma that arises from the ovary and is characterized by the presence of malignant epithelial cells that, in well differentiated tumors, resemble the epithelium of the fallopian tube or, in poorly differentiated tumors, show anaplastic features and marked nuclear atypia. "High FCGBP expression has previously been correlated with chemotherapy resistance in advanced ovarian serous adenocarcinomas." (PMID 38709264, 2024).
pancreatic neuroendocrine tumor (1 paper, 2020). Pancreatic endocrine tumor, also known as pancreatic neuroendocrine tumor (PNET), describes a group of endocrine tumors originating in the pancreas that are usually indolent and benign, but may have the potential to be malignant. "TTR and HP bound to fucose have been already proposed as a biomarkers of PDA; CDH5 in pancreatic neuroendocrine tumors developed in Von Hippel–Lindau disease patients and FCGBP in mucinous cysts in the pancreas and PDA." (PMID 32245227, 2020).
prostate adenocarcinoma (1 paper, 2024). "FCGBP at transcriptional levels was significantly reduced in prostate adenocarcinoma tissue from humans and transgenic mice." (PMID 38396056, 2024).
rectal cancer (1 paper, 2024). A primary or metastatic malignant neoplasm that affects the rectum. "Associations and comparisons between FCGBP expression and clinicopathological factors in 343 rectal cancer patients receiving chemoradiotherapy." (PMID 38709264, 2024). "A pathway enrichment analysis was performed to associate FCGBP expression with undisclosed biological functions in rectal cancer." (PMID 38709264, 2024). "The immunointensity of FCGBP staining exhibited a significant increase in tumor tissues associated with CRT-resistant rectal cancer." (PMID 38709264, 2024). "In our current study, we made the novel observation that FCGBP mRNA expression is increased in rectal cancer tissues with CRT resistance through bioinformatic transcriptome analysis." (PMID 38709264, 2024). "Subsequently, our investigation extended to a comprehensive examination of the expression levels and clinical significance of FCGBP in a larger rectal cancer cohort." (PMID 38709264, 2024). "Within this context, FCGBP emerged as the most markedly upregulated gene in CRT-resistant rectal cancer." (PMID 38709264, 2024). "The observed negative correlation between the response to gamma radiation and FCGBP expression supports the notion that FCGBP modulates CRT sensitivity in rectal cancer." (PMID 38709264, 2024). "To assess the clinical significance of FCGBP in rectal cancer, we conducted immunohistochemical staining to evaluate its immunointensity and correlation with clinicopathological variables within our rectal cancer cohort." (PMID 38709264, 2024). "In summary, our findings suggest that elevated FCGBP immunoexpression in rectal cancer significantly correlates with a poor response to CRT and diminished patient survival." (PMID 38709264, 2024). "To deepen our understanding of the biological functions of FCGBP in rectal cancers, we evaluated the expression correlation between FCGBP and genes of interest involved in significant biological pathways identified from the enrichment analysis." (PMID 38709264, 2024). "Consequently, the expression levels of FCGBP present a promising potential as a biomarker for predicting the prognosis of patients with rectal cancer undergoing preoperative CRT." (PMID 38709264, 2024). "Previous studies have hinted at the oncogenic properties of the Fc fragment of IgG binding protein (FCGBP) in various cancers; however, its clinical significance in rectal cancer remains unclear." (PMID 38709264, 2024). "Consequently, the expression of FCGBP emerges as a potentially valuable predictive and prognostic marker for patients with rectal cancer undergoing CRT." (PMID 38709264, 2024). "The observed correlations between FCGBP expression, poor responses to CRT, and inferior survival outcomes were subsequently validated in our specific rectal cancer patient cohort." (PMID 38709264, 2024). "Subsequent validation through immunohistochemical staining confirmed that heightened FCGBP expression is significantly correlated with an adverse response to CRT and unfavorable survival outcomes in our rectal cancer patient cohort." (PMID 38709264, 2024). "It is noteworthy that none of these studies have explored the correlation between FCGBP expression levels and the treatment response to CRT in rectal cancer." (PMID 38709264, 2024).
retinitis pigmentosa (1 paper, 2015). Retinitis pigmentosa (RP) is an inherited retinal dystrophy leading to progressive loss of the photoreceptors and retinal pigment epithelium and resulting in blindness usually after several decades. "In addition to these six pathways, frequent non-silent sequence mutations were found in FCGBP (immunoglobulin Fc gamma-binding protein; n=4) and USH2A (mutated in Usher syndrome and retinitis pigmentosa; n=4)." (PMID 25790293, 2015).
Sepsis (1 paper, 2020). Sepsis is defined as life-threatening organ dysfunction caused by a dysregulated host response to infection. "The other two highly expressed proteins that we observed in sepsis exosomes, immunoglobulin heavy constant Δ (IGHD) and Fc-fragment of IgG binding protein (FCGBP) are components of the inflammatory response." (PMID 32932765, 2020).